YTHDF3 (YTH N6-methyladenosine RNA binding protein F3)
Diseases named in the same sentence as YTHDF3 in open-access papers (continued):
Sharing a sentence is not in itself a finding about the gene and the disease.
viral infection (5 papers, 2016 to 2024). "The partial knockdown of YTHDF1 or YTHDF3 in Jurkat cells increased HIV-1 infection by three- to four-fold (p<0.005), while YTHDF2 knockdown slightly increased viral infection at 24 hpi." (PMID 27371828, 2016). "YTHDF3 negatively regulated type I IFN-mediated antiviral innate immune response, exerted its functions of promoting the virus replication; YTHDF3 defective mice effectively combated viral infections." (PMID 38448411, 2024). "Nevertheless, the mRNA level of YTHDF3 was significantly decreased at 24 hpi, but its protein expression level was equivalent to that of the control group without virus infection." (PMID 36819040, 2023). "Meanwhile, knocking down YTHDF2, but not YTHDF1 and YTHDF3, was conducive to the viral infection and replication." (PMID 33510385, 2021).
glioblastoma (4 papers, 2020 to 2025). The most malignant astrocytic tumor (WHO grade IV). "We used the TCGA microarray database and compared the mRNA expression levels of five YTH domain family proteins, YTHDF1, YTHDF2, YTHDF3, YTHDC1, and YTHDC2, between 720 normal brain tissue microarray datasets and 582 glioblastoma datasets." (PMID 33317545, 2020). "In addition, elevated levels were observed for RBM15B, WTAP, FTO, YTHDF2, YTHDF3, IGF2BP2, and IGF2BP3 in glioblastoma samples compared with normal brain controls." (PMID 38398118, 2024). "Although there are no reports documenting the function of YTHDF3 in glioblastoma, YTHDF3 is known to promote cancer cell interaction with brain endothelial cells and astrocyte blood–brain barrier extravasation, angiogenesis and outgrowth." (PMID 35625706, 2022).
myocardial infarction (4 papers, 2022 to 2026). Gross necrosis of the myocardium, as a result of interruption of the blood supply to the area, as in coronary thrombosis. "YTHDF3 variant rs4739066 showed a weak association with myocardial infarction (MI) in a genome-wide association study in Saudis of Arab descent." (PMID 37612540, 2023). "In the rat I/R model, YTHDF3 overexpression increased myocardial infarct size and impaired cardiac function, whereas CFTR overexpression attenuated the injury associated with YTHDF3 overexpression." (PMID 42265766, 2026).
abdominal aortic aneurysm (3 papers, 2022 to 2023). Enlargement and ballooning of the vessel that supplies arterial blood to the abdomen, pelvis and legs. "Another study shows that N1-Methyladenosine (m1A) regulation associated with the pathogenesis of abdominal aortic aneurysm through YTHDF3 modulating macrophage polarization." (PMID 37726690, 2023). "Overall, our research is the first to observe that N1-Methyladenosine (m1A) regulators related genes are associated with the pathogenesis of abdominal aortic aneurysm through YTHDF3 modulating macrophage polarization." (PMID 35620523, 2022).
breast tumor (3 papers, 2020 to 2021). "Several m6A regulators had significantly differential mRNA and protein expression in breast tumor and adjacent tissues, and m6A readers YTHDF1 and YTHDF3 might be good survival predictors." (PMID 34804948, 2021). "Furthermore, western blot revealed that the protein levels of METTL3, METTL14, and FTO were significantly lower in seven breast tumor samples randomly selected from RT-qPCR samples, while YTHDF1 and YTHDF3 had higher protein expression compared to adjacent tissues." (PMID 34804948, 2021).
liver fibrosis (3 papers, 2023 to 2024). "Accumulating evidence has shown that m6A-related enzymes regulate liver fibrosis; for example, Chaiet al. revealed that Mettl3 deficiency attenuated HSC activation and CCl4-induced liver fibrosis, and Liuet al. reported that the m6A reader YTHDF3 alleviated CCl4-induced liver fibrosis." (PMID 39175431, 2024). "In addition, a recent study revealed that the m6A reader YTHDF3 can influence TGF-β signaling pathway by mediating peroxiredoxin 3 translation in liver fibrosis." (PMID 37434186, 2023).
seminoma (3 papers, 2019 to 2021). A radiosensitive malignant germ cell tumor found in the testis (especially undescended), and extragonadal sites (anterior mediastinum and pineal gland). "Of relevance, higher VIRMA and YTHDF3 expression levels were observed in the seminoma-like TCam-2 cells compared to the analyzed NS cell lines, in line with our previous observations in primary tissues in silico analysis." (PMID 34446080, 2021).
clear cell renal cell carcinoma (2 papers, 2020 to 2024). "Unlike AML and clear cell renal cell carcinoma (ccRCC), among these 10 m6A regulatory genes, YTHDF3 exhibited the highest number of CNV gain events." (PMID 32547941, 2020).
colon cancer (2 papers, 2020 to 2022). "At present, only METTL3, YTHDF1, YTHDF3 was researched in colon cancer, other roles of m6A enzymes remain unclear." (PMID 32993738, 2020). "m6A reader YTHDF3 works as both a novel target of YAP and a key player in YAP signaling by facilitating m6A-modified lncRNA GAS5 degradation, which promotes the colon cancer progression." (PMID 32993738, 2020).
osteoporosis (2 papers, 2026). A condition of reduced bone mass, with decreased cortical thickness and a decrease in the number and size of the trabeculae of cancellous bone (but normal chemical composition), resulting in increased fracture incidence. "In summary, we delineate a melatonin/YTHDF3/DAPK2 protective axis that safeguards against unloading‐induced bone deterioration via post‐transcriptional regulation of Dapk2, thereby unveiling new mechanistic perspectives and therapeutic opportunities for disuse osteoporosis." (PMID 42149012, 2026).
osteosarcoma (2 papers, 2022 to 2025). A usually aggressive malignant bone-forming mesenchymal neoplasm, predominantly affecting adolescents and young adults. "In parallel, YTHDF3—a reader protein for m6A—directly drives aerobic glycolysis in osteosarcoma cells while accelerating tumor proliferation by recognizing and stabilizing PGK1 mRNA at specific m6A sites; this key glycolytic enzyme plays a pivotal role in metabolism." (PMID 41019082, 2025).
prostate carcinoma (2 papers, 2020 to 2025). A carcinoma that arises from epithelial cells of the prostate gland. "Conversely, the expression levels of the other two YTHDF family members, YTHDF2 and YTHDF3, were reduced in prostate cancer." (PMID 40251202, 2025). "The result has shown that gene-level deletion of YTHDF3 (HR 0.42, 95% CI 0.19-0.95), FTO (HR 0.57 95% CI 0.35-0.9) and amplification of ALKBH5 (HR 2.48 95% CI 1.39-2.42) were risk factors of prostate cancer biochemical recurrence." (PMID 32710725, 2020).
Stroke (2 papers, 2022 to 2025). Sudden impairment of blood flow to a part of the brain due to occlusion or rupture of an artery to the brain. "A recent study of blood samples of stroke patients predicted YTHDF3 as one of the seven key m6A regulators in the immune response." (PMID 40591025, 2025). "Additionally, we further showed that ALKBH5 and YTHDF3 proteins were changed at different times after stroke." (PMID 35747214, 2022).
thymoma (2 papers, 2022 to 2023). A neoplasm arising from the epithelial cells of the thymus. "To further illustrate the expression of YTHDF3, we selected 345 pairs of lung adenocarcinoma patients, 50 pairs of esophageal cancer patients, and 30 pairs of thymoma patients to monitor the immune response in cancer tissues and adjacent tissues by ELISAs." (PMID 36606187, 2022). "Similarly, the expression of YTHDC1 and YTHDF3 was negatively correlated with HS6ST2 in TGCT, but positively correlated with HS6ST2 in BLCA, COAD, UCEC, HNSC, PCPG, PRAD, SKCM, uterine carcinosarcoma (UCS), and thymoma (THYM)." (PMID 37932473, 2023).
thyroid cancer (2 papers, 2022 to 2023). "In contrast, YTHDF3 expression was low in Bladder Urothelial Carcinoma (BLCA), Thyroid carcinoma (THCA), UCEC, and Uterine Carcinosarcoma (UCS)." (PMID 36606187, 2022).
acne (1 paper, 2023). An inflammatory process of the sebaceous glands which is characterized by comedones, nodules, papules and/or pustules on the skin. "Overall, we demonstrate that a polysaccharide-conjugated and naturally derived oligopeptide HA-P5 can alleviate acne and act as an optimal FGFR2 inhibitor and reveal that YTHDF3 plays a crucial role in signalling between FGFR2 and AR." (PMID 36803994, 2023).
allergic asthma (1 paper, 2023). A asthma with a basis in a pathological type I hypersensitivity reaction. "It was notable that YTHDF3 abundance was also significantly reduced in the monocyte-derived macrophages from childhood allergic asthma." (PMID 37957139, 2023). "We detected a robust decrease of YTHDF3 levels in METTL3-deficient macrophages, and in monocyte-derived macrophages from children with allergic asthma." (PMID 37957139, 2023). "We next verified that, compared to 50 normal controls, the abundance of METTL3, METTL14, and YTHDF3 was significantly decreased in PBMCs derived from 55 childhood allergic asthma patients, recruited from the Children’s Hospital of Fudan University." (PMID 37957139, 2023).
Autoimmunity (1 paper, 2022). The occurrence of an immune reaction against the organism's own cells or tissues. "m6A elements (FTO, YTHDF2, YTHDF3, or YTHDC2) might target ISG15, stimulate the expression of ISG15, and activate the type I IFN signaling pathway, playing an active role in initiating the autoimmunity in pSS." (PMID 36465909, 2022).
bladder tumors (1 paper, 2021). "However, some m6A regulators, including METTL3, RBM15B, YTHDF1, YTHDF2, and IGFBP3, were significantly overexpressed in bladder tumors, and some m6A regulators, including METTL14, METTL16, ZC3H13, and YTHDF3, were markedly downregulated in bladder tumors." (PMID 35004726, 2021).
Cerebral ischemia (1 paper, 2024). Restriction of arterial blood supply to the brain associated with insufficient oxygenation to support the metabolic requirements of the tissue. "In a study exploring the relationship between m6A and circRNAs in mouse cerebral ischemia, the expression of YTHDF3 decreased and then increased, while the expression of METTL3 decreased." (PMID 38632288, 2024).
cervical intraepithelial neoplasia (1 paper, 2024). "Additionally, there was a positive correlation between increased YTHDF3 levels and the degree of cervical intraepithelial neoplasia (CIN) (P < 0.001)." (PMID 38250152, 2024).
endometriosis (1 paper, 2023). The growth of functional endometrial tissue in anatomic sites outside the uterine body. "For example, the first investigation into how m6A regulators function in endometriosis indicated that m6A regulators in endometriosis, such as METTL3, YTHDF2, YTHDF3, HNRNPC, HNRNPA2B1, and FTO, are significantly dysregulated compared with normal endometrial tissue." (PMID 36894952, 2023).
esophageal cancer (1 paper, 2022). A primary or metastatic malignant neoplasm involving the esophagus. "Our findings show that YTHDF3 expression had significant positive associations with MSI in stomach and esophageal carcinoma (STES), STAD, and CESC, while it had negative associations in DLBC, PRAD, HNSC, THCA, GBMLGG, BRCA, and LUAD." (PMID 36606187, 2022).
esophageal squamous cell carcinoma (1 paper, 2023). Esophageal squamous cell carcinoma (ESCC) is a type of esophageal carcinoma (EC) that can affect any part of the esophagus, but is usually located in the upper or middle third. "The EGR1 mRNA underwent m6A modifications through the action of METTL3, and YTHDF3 enhanced its RNA stability to upregulate the EGR1/Snail signaling pathway and support cancer metastasis in esophageal squamous cell carcinoma." (PMID 37012388, 2023).
HbH disease (1 paper, 2024). "The present study demonstrated that the knockdown of YTHDF3 facilitated the proliferation of K562 cells, and its low expression occurred in patients with HbH disease, which is consistent with the compensatory hematopoietic performance of such patients." (PMID 39088431, 2024). "This study revealed the downregulation of METTL16 and YTHDF3 in patients with HbH disease, possibly due to the compensatory response of the body to reduce the aggregation of HbH inclusion bodies on the red blood cell membrane, which leads to a decrease in the plasticity of red blood cells." (PMID 39088431, 2024). "YTHDF3 may read the m6A modification information of SLC5A3 mRNA, affect its protein expression regulate ROS synthesis and intracellular iron content in red blood cells and thus participate in the pathological and physiological processes of HbH disease." (PMID 39088431, 2024).
HCMV infection (1 paper, 2022). "The proportion of apoptotic cells during HCMV infection was significantly reduced after METTL3 or YTHDF3 knockdown." (PMID 35359726, 2022). "It was observed that the mRNA levels of METTL3, METTL14, YTHDF1, YTHDF2, and YTHDF3 were significantly increased in HAECs following HCMV infection." (PMID 35359726, 2022). "HCMV infection not only upregulated YTHDF3 expression but also promoted its binding to MCU mRNA, and this interaction was significantly decreased after METTL3 knockdown." (PMID 35359726, 2022). "Moreover, to identify the MCU RNA-binding domain of YTHDF3, we stably expressed YTHDF3 deletion mutants in HAECs followed by exposure to HCMV infection." (PMID 35359726, 2022). "YTHDF3 knockdown attenuated the MCU protein expression induced by HCMV infection but did not affect the MCU mRNA levels." (PMID 35359726, 2022). "Mechanistically, HCMV infection could induce aberrantly elevated m6A modification, especially the increases of methyltransferases-“writers” (METTL3) and m6A binding proteins-“readers” (YTHDF3)." (PMID 35359726, 2022).
Hepatitis (1 paper, 2025). Inflammation of the liver. "In conclusion, the rapid turnover of YTHDF1, YTHDF2, and YTHDF3 proteins during early ConA-induced hepatitis emerges as a hallmark of risk, suggesting their potential as crucial inflammation indicators in immune-mediated hepatitis." (PMID 40092485, 2025). "Initially, we investigated the protein expression of m6A readers, YTHDF1, YTHDF2, and YTHDF3, during the early stage of ConA-induced hepatitis and found that they were dramatically decreased in the liver." (PMID 40092485, 2025). "Notably, the deficiency of YTHDF1, but not YTHDF3, exacerbated hepatic injury, marked by heightened cytokine production and inflammatory cell infiltration during ConA-induced hepatitis." (PMID 40092485, 2025).
lung adenocarcinoma (1 paper, 2022). A carcinoma that arises from the lung and is characterized by the presence of malignant glandular epithelial cells. "We then detected YTHDF3 expression in cancer tissue and adjacent tissue samples from nine lung adenocarcinoma patients." (PMID 36606187, 2022). "YTHDF3 expression was also found to be upregulated in lung adenocarcinoma tissues compared with adjacent tissue samples." (PMID 36606187, 2022).
lymph node metastasis (1 paper, 2021). "The expression of METTL3, METTL14, WTAP, YTHDC2, YTHDF1, and YTHDF2 was remarkably higher in CRPC with lymph node metastasis than in CRPC with bone metastasis, whereas ALKBH5, FTO, and YTHDF3 were substantially decreased in CRPC with lymph node metastasis." (PMID 33403026, 2021).
myeloma (1 paper, 2022). "Paired differential analysis identified three of them (hnRNPA2B1, YTHDF3 and hnRNPC) are significantly upregulated in plasma cells of myeloma patients compared to normal plasma cells (Fold Change > 2)." (PMID 36451863, 2022).
Obesity (1 paper, 2021). Accumulation of substantial excess body fat. "METTL3 is differentially expressed between SAT and OVAT, whilst YTHDF3 associates with obesity and BMI in blood." (PMID 34950106, 2021). "In PBMCs, the eraser ALKBH5 and the readers YTHDF1 and YTHDF3 associate with obesity." (PMID 34950106, 2021). "We observe a correlation of two SNP markers in the YTHDF3 locus with its gene expression level suggesting that genetic variation underlying this reader protein may further impact on its potential role in obesity." (PMID 34950106, 2021). "However, in line with an association with obesity, expression of YTHDF3 is correlated to BMI." (PMID 34950106, 2021).
periodontitis (1 paper, 2024). An acute or chronic inflammatory process that affects the tissues that surround and support the teeth. "Notably, two m6A-related genes, WTAP and YTHDF3, showed higher expression in macrophages from periodontitis patients compared to healthy subjects." (PMID 39081311, 2024).
Pheochromocytoma and Paraganglioma (1 paper, 2022). "Notably, all DLBC and Pheochromocytoma and Paraganglioma (PCPG) cases with genetic changes (from 1% to 2% frequency) had missing copies of YTHDF3, and all Adrenocortical carcinoma (ACC) cases with genetic changes (~2% frequency) were mutation types." (PMID 36606187, 2022).
preeclampsia (1 paper, 2025). Preeclampsia is a hypertensive disorder of pregnancy that is characterized by new-onset hypertension with proteinuria presenting after 20 weeks of gestation, and depending on mild or severe forms may initially present with severe headache, visual disturbances, and hyperreflexia. "Because hypoxia is involved in the pathogenesis of preeclampsia, YTHDF3 may be involved in the pathogenesis of preeclampsia." (PMID 40356909, 2025).
pulpitis (1 paper, 2023). Inflammation of the dental pulp. "However, YTHDF1, YTHDF3, METTL16 and METTL3 gene expression were not statistically different between the pulpitis group and the control group, and RBM15B, ZCCHC4 and ALKBH5 were up-regulated." (PMID 37978362, 2023).
testicular cancer (1 paper, 2020). A primary or metastatic malignant neoplasm that affects the testis. "The m6A-related enzymes VIRMA and YTHDF3 have been implicated in testicular cancer." (PMID 32765970, 2020).
testicular germ cell tumor (1 paper, 2019). A germ cell tumor arising from the testis. "Herein, we assessed the differential abundance of m6A, its writer VIRMA and its reader YTHDF3, in testicular germ cell tumors (TGCTs), looking for clinicopathological correlates." (PMID 30866959, 2019).
thalassemia (1 paper, 2024). An inherited blood disorder characterized by a decreased synthesis of one of the polypeptide chains that form hemoglobin. "We found that the protein expression of METTL16 and YTHDF3 was significantly downregulated in HbH patients compared with normal controls without thalassemia." (PMID 39088431, 2024). "Then, we performed qRT-PCR and found that the relative expression of METTL16 and YTHDF3 mRNAs in patients with HbH and HbH-CS diseases was lower than that in normal controls without thalassemia." (PMID 39088431, 2024).
uveal melanoma (1 paper, 2025). A melanoma derived from melanocytes of the uveal tract. "Furthermore, within the scope of the same study, a set of genes including DERL1, FBXL17, MBOAT2,PLAG, SLC7A, and YTHDF3 were identified as target genes susceptible to modulation by miR-181b-5p in tumor tissue of uveal melanoma patients." (PMID 38914847, 2025).